IL6 (interleukin 6)
Diseases named in the same sentence as IL6 in open-access papers (continued):
Sharing a sentence is not in itself a finding about the gene and the disease.
gastric cancer (continued). "Strains expressing CagA strongly activate extracellular signal-regulated kinase 1/2 (ERK1/2), STAT3, and increase IL-6 and −11 levels, which results in the aggravating of HAG and gastric cancer." (PMID 40264171, 2025). "Gastric cancer-derived mesenchymal stromal cells (GC-MSCs) secrete high levels of IL-6 and IL-8 in the TME, leading to M2 macrophage polarization, promoting EMT, and facilitating gastric cancer metastasis." (PMID 40959082, 2025). "For example, they demonstrated that CAFs enhance the migration and EMT of gastric cancer cells by activating the Janus kinase 2/signal transducer and activator of transcription (JAK2/STAT3) pathway in gastric cancer cells by secreting IL-6." (PMID 40485724, 2025). "Overexpression of RBMS1 in HGC-27 and SGC-7901 cells increased the migration and invasion of gastric cancer cells by binding to the transcription factor MYC and activating the IL-6/JAK2/STAT3 signaling pathway." (PMID 41214391, 2025). "H. pylori-induced IL-6/IL-11 driving JAK/STAT3 activation plays a major role in the development and progression of gastric cancer." (PMID 40462044, 2025). "At the same time, studies have found that G protein coupled estrogen receptors prevent the activation of NF-κB promoter by Hp cytotoxin related gene A in gastric cancer cells, and inhibit the expression of tumor necrosis factor alpha (TNF-T), IL-6, and IL-1." (PMID 40463506, 2025). "Consistently, serum levels of IL-6 and TNF-α significantly increased with miR-3613-5p overexpression, indicating that miR-3613-5p promotes the progression from CAG to gastric cancer in mice." (PMID 40255569, 2025). "In patients with gastric cancer at stages I, II, and III of the disease, there is an increase in such proinflammatory cytokines as TNF-α, IL-2, IL-8, TNF-β, IL-17A, and IL-6, as well as a decrease in IFNγ." (PMID 40806737, 2025). "Asporin has been shown to strongly inhibit apoptosis, promote growth in gastric cancer cells, and selectively promote LEF1 binding to activate the promoters of PTGS2, IL-6, and WISP1 to facilitate their transcription." (PMID 39296492, 2024). "To further promote the development of enhanced recovery after surgery (ERAS) in laparoscopic gastric cancer (LGC) surgery, we evaluated and compared the predictive values of CRP, PCT, and IL-6 for infectious complications following LGC surgery." (PMID 38504206, 2024). "The secondary outcomes were the expression levels of TLR4 (Toll-like receptor), IL-6 and TNF-α in gastric cancer tissue." (PMID 38720250, 2024). "Administration of cytokine (IL-1, IL-6, IL-18, TNF) antagonists is the other therapy for gastric cancer patients." (PMID 39003350, 2024). "The JAK2/STAT3 pathway is also activated by stem cells in GC through high secretion of IL-6/IL-8, and this contributes to M2-like TAM polarization and, consequently, promotes gastric cancer metastasis." (PMID 38542388, 2024). "TFF1 impeded the combination of interleukin-6 (IL-6) with IL-6 Rα and further disrupted the activation of STAT3 in the gastric cancer cell lines AGS and STKM2." (PMID 38273295, 2024). "Jianzheng Wang and colleagues also reported that bone marrow fibroblasts (BMFs) can increase the expression levels of IL-6, TGF-β1, STAT3, and p-STAT3, thus promoting gastric cancer metastasis in a mouse model." (PMID 39309860, 2024). "This reduction in interaction decreases the transcriptional activation of IL-6, consequently attenuating the IL-6/STAT3 signaling-mediated expression of PD-L1 and M2 macrophage polarization, thus slowing the progression of gastric cancer." (PMID 39309860, 2024). "Other studies on gastric cancer have shown that the release of TNF‐α and IL‐6 activates NF‐κB signaling and upregulates PD‐L1 expression in tumor cells, consequently promoting the immune escape of tumor cells." (PMID 38660687, 2024).
gastric cancer (continued). "Inflammatory molecule IL-6, cell cycle regulator C-Myc, cell migration molecule MMP-9, and apoptosis molecule Caspase-3 exhibit significantly higher expression levels in the Gastric cancer group compared to the Control group (P < 0.01)." (PMID 38301047, 2024). "To explore the specific mechanism by which LDN reduces postoperative complications, we conducted scientific research on gastric cancer tissue and analysed the expression levels of TLR4, IL-6 and TNF-α." (PMID 38720250, 2024). "In our study, TNF, IL6, BCL2, PTEN, CTNNB1, and SRC are presented as common target genes between gastric cancer and AMK." (PMID 38612999, 2024). "We used this dataset to evaluate the expression patterns of YAP1, STAT3, IL11, IL6, TEAD1, IL6ST, and IL11RA in gastric cancer patients within the four TME subtypes." (PMID 37957015, 2024). "-Inhibits IL-6 expression, induces JAK and STAT3 phosphorylation, and down-regulates STAT3-mediated protein Bad, Bcl-2, and Bax expression to treat gastric cancer." (PMID 38397559, 2024). "The shedding of HAVCR-1 in gastric cancer increases the expression of IL-6 in RCC and activates the IL-6/STAT-3/HIF-1α pathway." (PMID 38831760, 2024). "BA inhibits gastric cancer stemness by regulating GRP78/TGF-β1 in gastric cancer cells, TAM polarization, and macrophage-derived IL-6 signaling in the tumor microenvironment." (PMID 36838713, 2023). "The most significant reduction in IL-6 and IL-8 concentrations was observed after the exposition of AGS gastric cancer cells to a combination of trastuzumab and Les-4367, compared with monotherapy and a combination of pertuzumab with Les-4367." (PMID 37047765, 2023). "EVs from gastric cancer(GC) cells treated with MLT promote the expression of TNF-α and CXCL10 in macrophages while suppressing IL-6 and MCP-1 expression, concurrently downregulating PD-L1 protein levels." (PMID 38087360, 2023). "IL-6 and TNF-α were the only cytokines presenting a significant increase upon both H. pylori infection and gastric cancer development." (PMID 37006300, 2023). "In gastric cancer, E2 treatment induces CD147 and IL-6 expression in ER-positive CAFs, increases MMP2 and MMP9 expression, and promotes cancer cell migration and invasion." (PMID 37509283, 2023). "We checked the effect of the tested combinations of drugs on IL-6 and IL-8 concentrations in AGS gastric cancer cells." (PMID 37047765, 2023). "IL-6 activated the STAT3 signaling pathway and induced cancer stemness by upregulating the expression of OCT4 and CD44 in gastric cancer cells." (PMID 36838713, 2023). "In this study, we examined the stemness of human gastric cancer cells at molecular level and the regulation of GRP78/TGF-β1-mediated TAM polarization and interleukin-6 (IL-6) secretion by BA." (PMID 36838713, 2023). "CAF-induced interleukin 6 (IL-6) and interleukin 11 (IL-11) activate the JAK-STAT3 pathway in gastric cancer (GC) cells." (PMID 35884907, 2022). "Among them, IL-6 activates the STAT3 pathway, and IL-1β can reduce gastric acid secretion, ultimately leading to the development of H. pylori gastritis or even gastric cancer." (PMID 36249768, 2022). "Promote the secretion of IL-6, IL-10, and VEGF, leading to immature differentiation of DCs and induction of gastric cancer." (PMID 36314013, 2022). "In gastric cancer, miRNA-149 mediates cancer cell EMT, invasion, and stemness through prostaglandin E2/IL-6 signaling in CAFs." (PMID 35327514, 2022). "Our previous study demonstrated the anti-metastatic function of piperine by blocking IL-1β-stimulated IL-6 via the downregulation of the p38 and STAT3 activation in gastric cancer TMK-1 cells." (PMID 35326180, 2022). "BALB/c nude mice treated only with hUC-MSC developed significantly greater tumor volumes than the control and the IL-6 pre-treated cells groups, revealing that this pre-treatment abolished the tumor-promoting effects of hUC-MSC in gastric cancer." (PMID 35955703, 2022).
gastric cancer (continued). "PPI network analysis showed that the main proteins through which CKI acts on gastric cancer cells include AKT1, IL6, MAPK1, and JUN." (PMID 35590327, 2022). "For example, miR‐98 can promote IVDD through the IL‐6/STAT3 signalling pathway, whereas miRNA‐558 promotes gastric cancer progression by attenuating Smad4‐mediated repression of heparinase expression." (PMID 35187741, 2022). "The inhibition of TGF-β1 secreted by gastric cancer cells prevented CAF activation through the suppression of α-SMA, MMP-9, TGF-β1, and IL-6." (PMID 35740372, 2022). "RA simultaneously inhibits the expressions of HIF-1α, IL-6, and signal transducers and activators of transcription 3 (STAT3), along with the phosphorylation of STAT3, suggestive of glycolytic inhibition in gastric cancer cells through the IL-6/STAT3 pathway." (PMID 36438836, 2022). "The induction of apoptosis is related to BAX overexpression, BCL-2 downregulation, and inhibition of inflammation, as revealed by the downregulation of IL-6, TNF-α, IL-1β, and IL-8 which modulate cell growth proteins in gastric cancer cells." (PMID 36359261, 2022). "Hence, we thought that the addition of agents (for example: IL-17A mAb, IL-6 mAb) against inflammation to the basic treatment including chemotherapy, palliative surgery etc would probably be a promising strategy for patients with initial stage IV gastric cancer." (PMID 35436305, 2022). "Hence, macrophages and IL-6 are hypothesized to play crucial roles in the cross-talk between gastric cancer cells and the immune microenvironment, and they also showed significant prognostic value in patients with gastric cancer." (PMID 36233285, 2022). "In our previous work, we demonstrated that LPE can reduce IL-6-induced migration/invasiveness and MMP-9/2 up-regulation in some gastric cancer cell lines." (PMID 34885656, 2021). "In gastric carcinoma, cancer cell–secreted TGF-β1 interacted with IL-6, thus inducing STAT3 activation and promoting the extensive metastasis of cancer cells." (PMID 34867344, 2021). "A recent study suggests that eEF1A1 is vital for the expression of IL-6 mediated by human oncostatin-M (OSM); however, currently there are very little information on the role of eEF1A1 in gastric cancer." (PMID 32636937, 2020). "We examined the role of IL-6 and IFN-γ in gastric cancer prevention by using the anti-inflammatory agent DFMO." (PMID 32231118, 2020). "In particular, the pro-inflammatory cytokines IL-6 and IFN-γ showed high and low expression in mice with gastric cancer induced by treatment with capsaicin and H. pylori, respectively." (PMID 32231118, 2020). "In this study, we worked out that H. pylori infection leads to higher mRNA expression of IL-6, JAK-2 and STAT-3 at the local site of infection which better explains the progression of gastric cancer at the molecular level." (PMID 33569347, 2020). "The results of the researchers showed that IL-6 was a chromatin assembly factor-1 (CAF)-specific secretory protein, which conferred gastric cancer cell chemoresistance by paracrine signaling." (PMID 32370233, 2020). "Using mouse models of gastric cancer, it has been reported that upregulation of IL-6 and activation of STAT-3 in H. pylori-infected gastric cancer ensues to activation of JAK/STAT signaling cascade." (PMID 33569347, 2020). "We found that production of the cytokines tested (IL-2, IL-4, IL-6, IL-10, IFN-γ) were up-regulated after exposure to gastric cancer derived exosomes." (PMID 32901082, 2020).
gastric cancer (continued). "The adipokine IL-6 is able to promote tumour growth and metastasis, while EGCG was able to inhibit IL-6 induced VEGF expression and angiogenesis in both in vitro and in vivo models of gastric cancer by suppressing STAT3 activity." (PMID 32731620, 2020). "A similar result was reported for HER2-overexpressing breast and gastric cancers, where hyperactivated STAT3 signaling-mediated trastuzumab resistance occurred via a feedback loop comprising FN/EGF/IL-6 upstream mediators." (PMID 32872659, 2020). "In gastric cancer, the lncRNA HOTTIP has been reported to promote IL-6 expression, inhibit T cell proliferation and promote immune escape in gastric cancer cells." (PMID 33173530, 2020). "The reconstitution of TFF1 protein in human gastric cancer cells and 3D gastric glands organoids from TFF1-KO mice abrogates IL6-induced nuclear p-STAT3Y705 expression." (PMID 31292446, 2019). "Chemerin promoted the growth and invasion of gastric cancer cells by inducing the phosphorylation of p38 MAPK and the expression of IL-6, vascular endothelial growth factor (VEGF), and matrix metalloproteinase-7 (MMP-7)." (PMID 31781638, 2019). "In acquired cisplatin-resistance and metastatic ovarian and gastric cancer cells, AKR1C1 is upregulated by IL-6 stimulation and nuclear factor erythroid 2-related factor 2 (Nrf2) and promotes chemoresistance." (PMID 31182137, 2019). "It was found that IL-6 and DYNC1I1 were positively correlated in gastric cancer with a correlation coefficient of 0.53 (P < 0.05)." (PMID 31249807, 2019). "Using AGS and STKM2 gastric cancer cell lines, we confirmed by Western blot analysis the activation and increase of phospho-STAT3 (Y705) in control cells after IL6 stimulation (100 ng mL−1) for 30 min." (PMID 31292446, 2019). "As cell invasiveness is strictly related to IL-6-induced upregulation of MMP-9 and MMP-2 expression levels in human gastric cancer cells, we have explored the effect of LPE in rIL-6 exposed MKN-28 and AGS cells." (PMID 31817563, 2019). "We analyzed the protective effect of LPE on IL-6-induced migration/invasiveness or MMP-9/2 up-regulation in MKN-28 and AGS gastric cancer cells." (PMID 31817563, 2019). "Given the fact that TFF1 is a secreted protein, AGS gastric cancer cell lines were treated with TFF1 recombinant protein (400 ng mL−1) for 24 h, followed by stimulation with IL6 (100 ng mL−1) for 30 min." (PMID 31292446, 2019). "Knockdown of IL-6 significantly decreased the number of colonies formed by HGC-27 and SGC-7901 gastric cancer cells by approximately 35.7% (P < 0.05) and 45.7% (P < 0.05), respectively." (PMID 31249807, 2019). "The gastric cancer patients with stage II/III and high IL-6 levels had a median survival of 618 days in contrast to 1418 days in patients with stage II/III and low IL-6 levels." (PMID 30038723, 2018). "Levels of IL-1β, IL-6, IFN-γ, and IL-10 were significantly higher and that of MCP-1 was lower in gastric cancer patients compared with controls." (PMID 28558708, 2017). "IFN-γ and IL-10 were significantly higher in both intestinal and diffuse gastric cancer, whereas IL-1β and IL-6 were higher and TGF-β lower only in intestinal gastric cancer; MCP-1 was lower only in diffuse gastric cancer." (PMID 28558708, 2017). "Subsequently, we hoisted STAT3 expression in gastric cancer cells by transfecting STAT3 plasmid and activated it by stimulating with IL-6." (PMID 29152078, 2017). "RelA expression in gastric cancer tissue strongly correlated with abundance of other tumor- and metastasis-promoting markers, including STAT3, MMP-9, IL-6 and VEGF." (PMID 28350359, 2017). "IL-6, NF-κB and VEGF protein and mRNA levels increased significantly in gastric cancer tissue compared with those in adjacent normal mucosa." (PMID 28350359, 2017). "The interleukin-6 (IL-6)/JAK/STAT3 signaling pathway plays a central role in inflammation-mediated cancers, including gastric cancer (GCa)." (PMID 27049718, 2016).
gastric cancer (continued). "Hs738 cells secreted IL-6 and CXCL1 more than did gastric cancer cell lines with the exception of MKN-1." (PMID 25785838, 2015). "To further evaluate the altered function of hUC-MSCs pre-treated with IL-6 in vivo, we co-transplanted the MSCs with SGC-7901 gastric cancer cells into nude mice." (PMID 25483835, 2015). "However, whether MSCs can be ‘educated’ by IL-6 to support gastric cancer remains unknown." (PMID 25483835, 2015). "Another relevant angiogenic factor is IL-6; high levels correlate with VEGF content in colorectal and gastric cancer." (PMID 24901008, 2014). "Overall, our findings provide the first evidence that increased IL-6/STAT3 activation correlates with aberrant immunity, leading to the progression and invasion of gastric cancer." (PMID 24116074, 2013). "We investigated the mRNA levels of IL-6, NF-κB and VEGF in gastric cancer tissue according to RT-qPCR." (PMID 23117246, 2013). "In the present study, we observed the levels of IL-6, IL-10 and VEGF in serum were significant decreased after removal of gastric cancer." (PMID 24116074, 2013). "IL-6, NF-κB and VEGF protein and mRNA levels increased significantly in gastric cancer tissue compared with those in adjacent normal mucosa tissue samples." (PMID 23117246, 2013). "In addition, the expression of NF-κB was positively correlated with the expression of IL-6 according to immunohistochemical and further correlation analysis, which suggests that the suppression of NF-κB or IL-6 may be a potential target for clinical therapy of gastric cancer in the future." (PMID 23117246, 2013). "The findings of the immunohistochemical staining confirmed a weak expression of NF-κB, IL-6 and VEGF in adjacent normal mucosa but a strong expression in gastric cancer tissue." (PMID 23117246, 2013). "Increased VEGF and survivin expression due to highly activation of IL-6/STAT3, helps gastric cancer cells to grow faster and to promote distant metastasis." (PMID 24116074, 2013). "In conclusion, our findings demonstrate that NF-κB, IL-6 and VEGF mRNA and protein levels increase significantly in gastric cancer tissues." (PMID 23117246, 2013). "Serum levels of IL-6 and TNF-α were significantly higher in patients with gastric cancer than gastritis." (PMID 23117246, 2013). "As expected, a single band was observed using each antibody, and the protein levels of IL-6, survivin, STAT3, p-STAT3 and VEGF in human gastric cancer tissues were all significantly higher than those in adjacent normal mucosa tissues (all P<0.001)." (PMID 24116074, 2013). "GMF isolated from human gastric cancer and H. pylori infected tissues co-cultured with CD4+ T cells induced substantially higher levels of Th17 than GMF from normal tissues in an IL-6, TGF-β, and IL-21 dependent manner." (PMID 23365642, 2013). "We further explored the protein expression of IL-6, NF-κB and VEGF in gastric cancer tissue according to western blotting." (PMID 23117246, 2013). "As we expected, a single band was performed using each antibody and the protein production levels of IL-6, NF-κB and VEGF in human gastric cancer tissue were all clearly upregulated compared to those in the adjacent normal mucosa tissue (all P<0.001)." (PMID 23117246, 2013). "Correlation between STAT3, survivin, IL-6, VEGF expression and TNM stages in gastric cancer patients." (PMID 24116074, 2013). "The principal objective of this study was to determine the relationship between serum IL-6 and CRP levels and malignant tendencies and prognosis in gastric cancer patients." (PMID 19457231, 2009). "The principal objective of this study was to determine the preoperative serum levels of IL-6 and CRP in gastric carcinoma, and to correlate them with disease status and prognosis." (PMID 19457231, 2009). "We investigated the expression level of interleukin-6 (IL-6) and SOCS-1 in gastric cancer cell lines." (PMID 15354212, 2004).